LGALS1 (galectin 1)
Diseases named in the same sentence as LGALS1 in open-access papers (continued):
Sharing a sentence is not in itself a finding about the gene and the disease.
cancer (continued). "The first study measured circulating galectin-1 in 989 individuals in Gothenburg, Sweden at the age of 40–65 years and investigated the association between serum galectin-1 and T2D independently of BMI, excluding individuals with a medical history of cancer or autoimmune diabetes." (PMID 36295832, 2022). "Galectin-1 has been implicated in the metastasis of many cancers, including PDAC." (PMID 33917370, 2021). "Therefore, numerous investigations are being carried out to identify potential targets such as galectin-1, cancer associated cathepsins, OX40+Foxp3+ Treg cells, etc., to develop new therapies and to achieve greater treatment efficacy." (PMID 32645977, 2020). "CHIP and Galectin-1 are associated with the development of metastasis in cancer." (PMID 32025218, 2020). "Galectin-1 which expressed in cancer-associated fibroblasts (CAFs) could promote the invasiveness of GC cells by binding to LacNAc of β1 integrin on the cell surface." (PMID 31355147, 2019). "Galectin-1 is a hypoxia-induced angiogenic factor associated with cancer and proliferative DR." (PMID 29170525, 2017). "In addition to its role in tumorigenesis, the association between galectin-1 expression and chemoresistance was investigated in several types of cancer more recently." (PMID 28842515, 2017). "CLU, NDRG1, CD166, S100A11 and Galectin-1 were associated with carcinoma and Galectin-3." (PMID 28701735, 2017). "Galectin-1 and galectin-3 are expressed by virtually all immune cell lineages, including monocytes, macrophages, T cells, NK cells, B cells, and dendritic cells, and have also been implicated in cancer immunology." (PMID 26589797, 2016). "All the results indicated that the Galectin-1 was mainly expressed in cancer-associated PSCs." (PMID 24595374, 2014). "Furthermore, several immunosuppressive cells were identified to reprogram the metastatic ecosystem, including FOXP3+ regulatory T (Treg) cells, LAMP3+ tolerogenic DCs (tDCs), CCL18+ M2‐like macrophages, RGS5+ cancer‐associated fibroblasts, and LGALS1+ microglial cells." (PMID 36529697, 2023). "Furthermore, the multivariate survival analysis indicated that staining intensities of Galectin-1 in cancer-associated stromal cells (p<0.001), pT category (pT3/pT4) (p = 0.041) and pN category (pN1) (p = 0.017) remained significant independent prognostic factors." (PMID 24595374, 2014). "As a factor involved in tumor progression, Galectin-1 (Gal-1) plays a role in cancer immune escape and induces T-cell apoptosis." (PMID 40768094, 2026). "We analyzed the expression of galectin-1 and miR-22-3p using cancer tissues and the correlation with clinical pathological characteristics." (PMID 39996781, 2025). "Galectin 1 is important in cancer as it suppresses immune functions in tumor environments, aiding tumors in avoiding immune detection." (PMID 39996744, 2025). "The molecular mechanisms by which the miR-22-3p/galectin-1 axis is involved in cancer progression need to be further investigated." (PMID 39996781, 2025). "Notably, in a hypoxic microenvironment, Galectin-1 secreted by cancer-associated fibroblasts (CAFs) is further upregulated, which may drive the drug-resistant phenotype by activating the VEGF, suggesting its potential as a target for reversing rituximab resistance." (PMID 41189944, 2025). "LGALS1 was found to be expressed by fibroblasts, pericytes, and myeloid cells, all of which upregulate its expression in cancer compared to normal tissue." (PMID 38384845, 2024). "Galectin 1 from fibroblasts and TGFβ have previously been shown to synergistically foster cancer cell proliferation and metastasis." (PMID 39324702, 2024). "The beta-galactoside-binding mammalian lectin galectin-1 can bind, via its carbohydrate recognition domain (CRD), to various cell surface glycoproteins and has been implicated in a range of cancers." (PMID 38928409, 2024).
cancer (continued). "Studies have identified that RTKs are a major contributor to drug resistance in cancer cells and Galectin-1 mediates RTK activation to induce HCC progression." (PMID 37433225, 2023). "Treatment with AXL and MET inhibitors successfully abolished Galectin-1 overexpression–mediated cancer stemness." (PMID 37433225, 2023). "The importance of intracellular galectins in cancer progression goes back decades ago but attracted the attention of many when it was shown that galectin-1 binds activated H-Ras, stabilizing its anchorage to the cell membrane." (PMID 37753083, 2023). "Cancer cell 2 expressed high levels of mesenchymal/basal-like subtype genes including Lgals1, Fbln2, Timp1, and Areg." (PMID 37998349, 2023). "Orozco and colleagues have also shown that it is possible to use siRNA to deplete galectin-1 in pancreatic stellate cells, which inhibited cancer progression and metastasis when co-injected with pancreatic tumor cells." (PMID 37753083, 2023). "Collectively, our data demonstrate that the knockdown of Galectin-1 reversed sorafenib resistance, reduced cancer stemness, and enhanced sorafenib-mediated ferroptosis." (PMID 37433225, 2023). "Knockdown of galectins using ASOs has been extensively used to demonstrate the role of galectin-1 and galectin-3 in cancer." (PMID 37753083, 2023). "Galectin-1 has been observed to arbitrate the adhesion of cancer cells to the ECM; laminin, fibronectin, and other glycoproteins presented in the basement membrane provide the necessary epitopes for Galectin-1-cell-ECM cross-linking." (PMID 34693476, 2022). "Galectin-1 is considered an immunomodulatory protein involved in the body’s normal immune response and the development of cancer by regulating the function of immune cells." (PMID 36428567, 2022). "LGALS1 (Galectin-1), a β-galactoside binding mammalian lectin, is overexpressed in NSCLC and is associated with cancer progression and immune disorders." (PMID 35180865, 2022). "Data from other types of cancers support a model in which the ability of extracellular Galectin-3 and Galectin-1 to bind to cell surface glycoproteins is regulated by the exact composition of the glycan structures attached to client proteins." (PMID 36430839, 2022). "Lgals1, a carbohydrate-binding protein, is significantly increased in the RCC cancer tissue and is implicated in cancer cell proliferation, invasion." (PMID 35308536, 2022). "Keeping with these findings, Galectin-1 and MUC16 have been associated with EMT in different kinds of cancer, including PDAC18–20." (PMID 35017635, 2022). "Galectin-1 is involved in promoting the survival of many cancers including hematopoietic malignancies." (PMID 36430839, 2022). "By binding to its glycosylated ligands, extracellular galectin-1 is able to regulate tissue development, immune system activation, pathogen infection and cancer progression." (PMID 35927755, 2022). "We also found a correlation between LGALS1 expression levels and the ability of H-1PV to induce oncolysis in 59 cancer cell lines." (PMID 35632759, 2022). "In fact, overexpression of galectin-1 in cancer cells and/or stromal cells is observed to be correlated with poor prognosis in many types of cancers." (PMID 35927755, 2022). "Glycan–Galectin interactions are known to regulate B-cell function and Galectin-1 plays a role in immune modulation as well as in cancer." (PMID 35371997, 2022). "Meanwhile, galectin-1 interacts with various other malignant immune cells, which play a pro-cancer role in PDAC." (PMID 36428567, 2022). "In this study, we revealed that H-1PV also interacts at the cell surface with galectin-1 and uses this glycoprotein to enter cancer cells." (PMID 35632759, 2022). "Owing to the overexpression of galectin-1 in different cancer cell lines, the protein has been proposed as a potential target for therapeutic intervention and a predictive diagnostic marker." (PMID 34482478, 2022).
cancer (continued). "Galectin-1, 7, and 9 have been found to be overexpressed in cancer cells and therefore represent highly relevant targets in cancer diagnostics." (PMID 34350156, 2021). "Galectin-1 (GAL-1) is linked to cell adhesion, migration, survival, and signaling and is associated with inflammatory disorders, cancer, and with proliferative diabetic retinopathy." (PMID 33562561, 2021). "Galectin-1 produced by cancer cells or by normal cells of the microenvironment is a major regulator of the cancer-stroma crosstalk." (PMID 34356834, 2021). "The galectin-1 has been found to be involved in poor outcomes after treatment of a variety of cancers." (PMID 34201887, 2021). "We first searched the ONCOMINE database of published microarray data with matched normal and cancer specimens, and found, in the Kaiser Colon database, that a higher expression of both LGALS1 and SOX9 are seen in CRC samples than in normal colon samples." (PMID 34568045, 2021). "Though galectin-1 and galectin-3 are also immunomodulators, galectin-9 is widely considered to be the strongest immune modulator related to cancer." (PMID 32033052, 2020). "Recent studies have found that Galectin-1 (GAL-1) is highly expressed in a variety of malignant tumors, and that it is involved in various malignant functions, including tumorigenesis, development, invasion and metastasis, angiogenesis and immune escape." (PMID 33170154, 2020). "Several signaling pathways in which LGALS1 is involved have been shown to promote the progression of cancer cells, such as H-Ras-dependent pathway 50, MAPK JNK/p38 pathway 51, and Akt/ERK1/2 signaling pathway." (PMID 32047564, 2020). "Our attention was caught by the relatively poorly investigated NRP1 ligand Galectin-1 (Gal-1), encoded by the gene LGALS1, which has been associated with cancer progression in numerous studies and is also considered a potential therapeutic target." (PMID 32784465, 2020). "Multivalent interactions between galectin-1 and glycoproteins in the extracellular matrix contribute to cancer metastasis." (PMID 31996694, 2020). "LGALS1 (galectin 1) is a β-galactoside-binding protein that recognizes glycoconjugates and regulates cell proliferation, differentiation and apoptosis in cancer." (PMID 32742447, 2020). "Increasing evidence has suggested that galectin-1 is elevated in cancer tissues and a high expression level of galectin-1 is associated with poor OS and DFS in different cancer types, particularly in digestive cancers." (PMID 31832021, 2019). "On the other hand, galectin-1 diminishes resistance of cancer cells to anoikis, which is a typical feature of cancer cells." (PMID 30925774, 2019). "Galectin-1 (Gal-1) is considered one of the representative galectins and is upregulated in many cancers, including EOC." (PMID 31581131, 2019). "Galectin-1 (Gal-1) is an immunosuppressive glycan-binding protein, which is up-regulated in several types of cancers including glioblastoma." (PMID 31225500, 2019). "On the other hand, it still poses a major challenge to translate current knowledge into the design and development of effective galectin-1 inhibitors in cancer therapy." (PMID 29498681, 2018). "Currently, no documented literature has reported the relationship between FABP 4 and galectin-1 in cancer cells." (PMID 29671787, 2018). "The carbohydrate-recognition domain of extracellular galectin-1 can bind to carbohydrates located at the cell surface of cancer and stromal cells." (PMID 30140386, 2018). "Further research is needed to investigate the role of galectin-1 in the complex interaction between cancer and stromal cells leading to the aggressive behavior of cancer cells." (PMID 30140386, 2018). "In cancer, galectin-1 (Gal-1) and galectin-3 (Gal-3) are the most well-studied galectins and both have been shown to enhance cell proliferation, signaling, and migration." (PMID 30135430, 2018).
cancer (continued). "This review focuses on the biological effects of galectin-1, galectin-3 and galectin-9 in various cancers and discusses anticancer therapies that target these molecules." (PMID 29389859, 2018). "Most studies investigated the expression of galectin-1 in cancer epithelial and immune cells while we found an increased expression of galectin-1 in stroma-high tumors." (PMID 30140386, 2018). "Other proteins in clusters 6 and 9, including annexin isoforms, cofilin-1, galectin-1 and coactosin-like protein, are also known to play different roles in cancers." (PMID 30440021, 2018). "In both MCF-7 and UM-UC-3 cancer cells, we found increased protein levels of galectin-1 and GLUT1 in spheroids compared to their respective monolayers." (PMID 28545086, 2017). "PDT efficacy with glycosylated PS (specifically those conjugated with glucose or galactose) is highly dependent on metabolism of cancer cells, the redox state of the cell, and expression of proteins such as galectin-1 and glucose transporter 1 (GLUT1)." (PMID 28545086, 2017). "Although many studies have focused on the role of galectin-1 in cancer progression, relatively little attention has been paid to galectin-1 as an extracellular therapeutic target." (PMID 28415760, 2017). "Asialofetuin binds to the lectins galectin-1 and galectin-3, which are located on the surface of cancer cells, and induces homotypic aggregation by serving as a cross-linking bridge between adjacent cells." (PMID 29185464, 2017). "Taken together, these results suggest that extracellular galectin-1 contributes to cancer progression and doxorubicin resistance in TNBC cells." (PMID 28415760, 2017). "Our results indicate that PSC-derived Galectin-1 induces EMT of cancer cells through activating the NF-κB pathway." (PMID 29156810, 2017). "The role of Galectin-1 in cancer has been studied by various groups, and several papers already exist on this topic." (PMID 28594391, 2017). "Hypoxia-inducible factor (HIF)-1α, a master transcription factor for cellular response to hypoxia, was shown to regulate LGALS1 mRNA expression in cancer cells." (PMID 29170525, 2017). "In conclusion, our findings indicate that galectin-1 plays a pivotal role in the regulation of key processes in cancer cells, such as migration, invasion, and chemoresistance, by modulating FAK and ERK signaling and survivin level." (PMID 28415760, 2017). "Of the differentially expressed proteins, CLU, NDRG1, CD166, S100A11 and Galectin-1 were carcinoma-related proteins affected by rGal3C." (PMID 28701735, 2017). "These synthetic multivalent systems serve as important tools for studying galectin-1 mediated cancer cellular functions." (PMID 27649167, 2016). "Knockdown of galectin-1 in cancer cells decreased the upregulation of TDO2 and consequently reduced Kyn production in LCAF." (PMID 27050278, 2016). "Although the mechanisms of action of galectin-1 in these processes are still not well understood, the overexpression of galectin-1 in cancer progression indicates that the role of galectin-1 is significant." (PMID 27649167, 2016). "A comprehensive list of cancer cell types in which galectin-1 has been observed to mediate migration and invasion is provided in a recent review." (PMID 27649167, 2016). "Galectin-1 has been reported to mediate homotypic aggregation of cancer cells through multivalent interactions with cell-surface glycoconjugates in a variety of cell types." (PMID 27649167, 2016). "In order to develop robust multivalent galectin-1 therapeutics, a better understanding of galectin-1 mechanisms in cancer is paramount." (PMID 27649167, 2016). "The synthetic multivalent frameworks have served as important tools to establish the role of multivalent binding interactions for the galectin-1 mediated advancement of cancer processes." (PMID 27649167, 2016).
cancer (continued). "Compelling evidence gathered over recent decades indicate galectin-1, to be amongst the unique repertoire of proteins overexpressed across a spectrum of human cancers." (PMID 27223428, 2016). "An understanding of the impact that valency has on galectin-1 mediated cancer processes is important for advancement of our mechanistic understanding of the impacts of galectin-1 on cancer progression." (PMID 27649167, 2016). "Relevant to cancer cell biology, intracellular galectin-1 participates in protein–protein interactions with H-Ras, protocadherin-24, and Gemin4 in a carbohydrate-independent manner." (PMID 27649167, 2016). "Although with different binding affinities, other galectin members also recognize TF antigen and several of them, such as galectin-1, galectin-2, -4, and -8, are shown to also have elevated levels in the circulation of cancer patients." (PMID 27066458, 2016). "Our findings therefore suggest that inhibition of galectin-1 can increase the anti-cancer activity of cisplatin." (PMID 26859293, 2016). "Although homotypic cellular aggregation, cellular adhesion to the ECM, metastasis, angiogenesis, and apoptosis are highlighted here, additional processes in which multivalent binding by galectin-1 is involved in cancer progression are likely." (PMID 27649167, 2016). "Taken together, these studies indicate that galectin-1 inhibition is a promising therapeutic strategy against cancer." (PMID 27649167, 2016). "Among human galectins, galectin-1 and -3 gained most attention due to their cancer-related activities." (PMID 27066458, 2016). "For example, the metastatic spread of cancer occurs in part through interactions between galectin-1 and glycoproteins in the ECM, such as laminin and fibronectin." (PMID 27649167, 2016). "Of the 15 members of the lectin family, galectin-1 and galectin-3 appear to be the major players in cancer biology and, therefore, have stimulated significant research interest." (PMID 27649167, 2016). "The levels of galectin-1 expression in cancer cells were analyzed to the pathologic and clinical information." (PMID 26589590, 2015). "In most cases, galectin-1 is up-regulated in cancer cells as reported in thyroid carcinoma by Chiariotti and by Xu." (PMID 26589590, 2015). "This is a 15-fold increase in the concentration of lactose required to disrupt galectin-1 mediated cancer cell adhesion compared to the multivalent counterpart." (PMID 26124876, 2015). "The influence of host-derived versus cancer cell–derived galectin-1 on cancer progression remains to be further elucidated." (PMID 26589590, 2015). "Next, glycodendrimers were added to cancer cells to modulate galectin-1 mediated cellular aggregation." (PMID 26124876, 2015). "In contrast to the results of galectin-1 staining in the cancer cell, statistical analysis of the data revealed the staining results of the stromal cells showed significant correlation with pathologic variables of the EOC patients." (PMID 26589590, 2015). "Hypoxia-inducible factor (HIF)-1α protein, an oxygen-sensitive subunit of HIF-1 that is a master factor for cellular response to hypoxia, regulates LGALS1/Galectin-1 mRNA in cancer cells." (PMID 26648523, 2015). "Galectin-1 has been found to be more effective on various carcinomas including epithelial tumors, galectin-7 on thyroid tumors, galectin-8 on colon cancer, and galectin-12 on fibroblast cells." (PMID 25730388, 2015). "Secondly, galectin-1 can be synthesized by stromal cells, especially stromal fibroblasts, as they get stimulated by oncologic signals from carcinoma cells or from ECM during ECM remodeling." (PMID 26589590, 2015). "Firstly, galectin-1-expressing carcinoma cells can synthesize and secrete galectin-1into stromal cells using its non-classical secretory pathway." (PMID 26589590, 2015). "So, it will be well accepted that Galectin-1 expression or overexpression in tumors and/or the tissue surrounding them must be considered as a sign of the malignant tumor progression." (PMID 24595374, 2014).